CUL4A (cullin 4A)
Diseases named in the same sentence as CUL4A in open-access papers (continued):
Sharing a sentence is not in itself a finding about the gene and the disease.
ovarian carcinoma (6 papers, 2019 to 2022). A malignant neoplasm originating from the surface ovarian epithelium. "MiR-377 and miR-494 were reported as negative regulators of CUL4A expression in ovarian cancer, and significantly reduced the migratory ability of cancer cells." (PMID 34257560, 2021). "In an effort to further understand the biological role of CRL4 in cisplatin resistance of ovarian cancer, we first knocked down Cul4A and DDB1, respectively, with shRNAs and examined cell viability in response to cisplatin treatment." (PMID 30718461, 2019). "Silencing of the CRL4 E3 ubiquitin ligase complex ROC1 and CUL4A genes by siRNA significantly decreased the expression of CFP1 and BST2, consistent with that observed after MLN4924 treatment of ovarian cancer cells." (PMID 35864225, 2022). "To confirm that the pharmacological effects of MLN4924 were due to disrupting CRL4s, we silenced RBX1 (ROC1) and CUL4A, the core component of CRL complexes, in ovarian cancer A2780 and ES-2 cells." (PMID 35864225, 2022). "In ovarian cancer, depleting CUL4A mimics MLN4924-induced death, and depleting the replication origin licensing factor CDT1, a CUL4A target, rescues these effects." (PMID 32123578, 2020). "To detect the expression of CRL4 in ovarian cancer, we examined the levels of CRL4 (Cul4A and DDB1) E3 ligase in ovarian cancer tissues and normal interstitial tissues." (PMID 30718461, 2019). "We found that CRL4 was upregulated in ovarian cancer and that knockdown of CRL4 (Cul4A/DDB1) inhibited cell proliferation and migration, and increased apoptosis in cisplatin-resistant ovarian cancer cells." (PMID 30718461, 2019). "To identify whether CRL4 is also involved in cisplatin resistance, we examined the expression levels of Cul4A and DDB1 in cisplatin-sensitive ovarian cancer cell A2780 and cisplatin-resistant cell A2780CP by western blot and QRT-RCR." (PMID 30718461, 2019). "Interestingly, we found that both Cul4A and DDB1 expression levels were increased in A2780CP compared with that in A2780, suggesting CRL4 may play a key role in triggering cisplatin resistance of ovarian cancer." (PMID 30718461, 2019). "Furthermore, a recent study suggested that DDB1 and Cullin-RING ubiquitin ligases (CRL) 4, the ubiquitin ligase of Cullin 4A (CUL4A)-DDB1 E3, are important factors in ovarian cancer chemoresistance because they regulate apoptosis and might be therapeutic targets for patients after cisplatin failure." (PMID 31842285, 2019).
osteosarcoma (5 papers, 2015 to 2020). A usually aggressive malignant bone-forming mesenchymal neoplasm, predominantly affecting adolescents and young adults. "CUL4B mRNA and protein were both specifically overexpressed in these human osteosarcoma cell lines, although CUL4A also exhibited a slight induction under the same conditions." (PMID 28446751, 2017). "Cul4A has been reported to promote cancer metastasis and invasion in osteosarcoma cells." (PMID 31052599, 2019). "Consistently, western blot (WB) analysis also indicated that the CUL4B protein was significantly induced (~3–4-fold induction) in all four osteosarcoma cell lines and that CUL4A was slightly overexpressed (~1.3–1.6-fold induction), whereas other Cullin family proteins were not." (PMID 28446751, 2017). "Interestingly, NSC1892 also showed promising cytotoxicity to decrease the growth of other CUL4A- or CUL4B-overexpressing tumor cells such as SKOV3 ovarian cells and Saos2 osteosarcoma cells." (PMID 32140073, 2020). "Additionally, the expression of CUL4A, a paralogue of CUL4B, was slightly increased (~1.5‐fold induction) in osteosarcoma cells compared to osteoblast cells." (PMID 29377600, 2018). "Among the other six Cullins, only CUL4A was slightly overexpressed (~1.4–1.7-fold induction) in osteosarcoma cells, but not the other five Cullins, including CUL1, CUL2, CUL3, CUL5 and CUL7." (PMID 28446751, 2017). "To validate this hypothesis, we selected a CUL4A-overexpression ovarian cell line SKOV3 and a CUL4B-overexpression osteosarcoma cell line Saos2 and evaluated their cell proliferation abilities in the conditions of 0, 0.2, 2 and 20 μM NSC1892 treatments, respectively." (PMID 32140073, 2020).
intrahepatic cholangiocarcinoma (4 papers, 2015 to 2021). A carcinoma that arises from the intrahepatic bile duct epithelium in any site of the intrahepatic biliary tree. "The role of CUL4A in intrahepatic cholangiocarcinoma (iCCA) has been rarely explored." (PMID 34257560, 2021). "We examined two iCCA cell lines and 86 cases of intrahepatic cholangiocarcinoma to analyze copy number of three target genes, including cullin 4A (CUL4A), insulin receptor substrate 2 (IRS2), and transcription factor Dp-1 (TFDP1) at 13q34 by quantitative real-time polymerase chain reaction." (PMID 26684807, 2015).
male infertility (4 papers, 2014 to 2023). The inability of the male to effect fertilization of an ovum after a specified period of unprotected intercourse. "Null mutation of Cul4a leads to male infertility characterized by oligozoospermia, asthenozoospermia, and teratozoospermia, due to meiotic progression defects at the pachytene stage and subsequent germ cell death." (PMID 34685710, 2021). "Indeed, the CUL4 E3 ubiquitin ligase plays a central role in mammalian spermatogenesis, as shown by male infertility observed in null mutations of the Cul4A or Cul4B genes in mice." (PMID 37689310, 2023). "Disruption of Cul4A caused male infertility because of the defective meiotic progression." (PMID 29907856, 2018). "Disruption of Cul4A in mice resulted in male infertility due to abnormal meiotic progression, whereas disruption of Cul4B in mice caused male infertility because of aberrant post-meiotic sperm development." (PMID 29907856, 2018). "Indeed, two converging studies in mice recently showed that cullin 4 is also required for meiosis also in mammals, as depletion of Cul4a (one of the two mammalian Cul4 genes) led to male infertility." (PMID 25116939, 2014).
esophageal squamous cell carcinoma (3 papers, 2014 to 2022). Esophageal squamous cell carcinoma (ESCC) is a type of esophageal carcinoma (EC) that can affect any part of the esophagus, but is usually located in the upper or middle third. "Since CUL4A has been previously reported to be overexpressed in nasopharyngeal and esophageal squamous cell carcinoma, this provides further rationale for the investigation of pevonedistat for HNSCC therapy." (PMID 35428778, 2022).
mesothelioma (3 papers, 2015 to 2019). A usually malignant and aggressive neoplasm of the mesothelium which is often associated with exposure to asbestos. "In our previous study, we observed that Cul4A knockdown is associated with G0/G1 cell cycle arrest through up‐regulation of p21 in mesothelioma cells." (PMID 26969027, 2016). "We next analysed the association of Cul4A and Gli1 protein expression in 71 mesothelioma tumours (excluding two missing samples) and seven mesothelioma cell lines." (PMID 26218750, 2015). "Statistical analysis revealed a significant association of Cul4A and Gli1 expression in these mesothelioma samples (P < 0.05, chi-square test)." (PMID 26218750, 2015). "To further our understanding on the association of Cul4A and Gli1 expression in mesothelioma cells, we analysed mTOR expression after Cul4A knockdown by siRNA and mTOR expression was decreased." (PMID 26218750, 2015). "Cul4A expression also associated with Gli1 expression in mesothelioma tumours and in human mesothelioma cells, and inhibiting Cul4A expression by siRNA decreased Gli1 expression in mesothelioma cells." (PMID 26218750, 2015). "The increased Cul4A expression is associated with Gli1 expression in both mesothelioma tumours and in mesothelioma cells, and inhibiting Cul4A expression by siRNA decreased Gli1 expression in mesothelioma cells." (PMID 26218750, 2015). "Because Gli1 is highly expressed in human mesothelioma cells, we compared Cul4A and Gli1 expression in mesothelioma tumours and found their expression associated (P < 0.05, chi-square)." (PMID 26218750, 2015). "Our analysis of mesothelioma cell lines showed that Cul4A and Gli1 expression is associated, which is similar to our observation in mesothelioma tumours." (PMID 26218750, 2015). "Further study is needed to evaluate this hypothesis and understand the mechanism that underlies the increase in Gli1 expression when Cul4A is overexpressed in human mesothelioma." (PMID 26218750, 2015). "In conclusion, our results suggest Cul4A overexpression, driven by increased Cul4A copy number, in mesothelioma tumours and in mesothelioma cells." (PMID 26218750, 2015). "When Gli1 mRNA expression in the cell lysates was analysed using qRT-PCR, all the mesothelioma cell lines showed decreased Gli1 expression levels after Cul4A knockdown (P < 0.05, t-test)." (PMID 26218750, 2015). "In human mesothelioma cells, down-regulation of Cul4A by shRNA induced cell cycle arrests in G0/G1 and inhibited the growth of mesothelioma cells." (PMID 26218750, 2015). "Among 30 mesothelioma samples with moderate Cul4A expression, 33.3% showed weak Gli1 expression and 10.0% showed moderate or strong Gli1 expression." (PMID 26218750, 2015). "In this study, we analysed clinical mesothelioma tumours and found moderate to strong expression of Cul4A in 70.9% (51/72) of these tumours, as shown by immunohistochemistry." (PMID 26218750, 2015). "In this study, we analysed mTOR protein level after Cul4A inhibition by siRNA, and our results showed that mTOR protein level was reduced faster in mesothelioma cells when Cul4A transcription was inhibited." (PMID 26218750, 2015). "In this study, knocking-down Cul4A expression by using siRNA showed that Gli1 mRNA level and Gli1 protein level were both decreased in the treated mesothelioma cells, suggesting that inhibiting Cul4A decreased Gli1 expression." (PMID 26218750, 2015). "Three mesothelioma cell lines (MS-1, H2452 and 211H) with increased Cul4A copy number were treated with Cul4A siRNA for 48 hr and greater than 90% reduction in Cul4A mRNA was detected in all cell lines when compared to controls (*P < 0.05, t-test)." (PMID 26218750, 2015). "Our previous study has shown that Cul4A inhibition induces cell cycle arrests and reduces mesothelioma cell growth." (PMID 26218750, 2015). "Our FISH analysis showed that some mesothelioma tumours with moderate to strong Cul4A expression showed two copies of Cul4A." (PMID 26218750, 2015).
mesothelioma (continued). "Among the six mesothelioma cell lines that had moderate to strong Cul4A expression, four cell lines showed moderate to strong Gli1 expression." (PMID 26218750, 2015). "Our study shows that in mesothelioma tumours and human mesothelioma cell lines, Cul4A is overexpressed and Cul4A copy number is increased." (PMID 26218750, 2015). "The increased Cul4A copy number and its association with Gli1 regulation in mesothelioma cells highlight Cul4A as a possible new therapeutic target for mesothelioma tumours." (PMID 26218750, 2015). "In 72.2% mesothelioma tumours with increased Cul4A copy number identified by fluorescence in situ hybridization analysis, Cul4A protein expression was moderate to strong." (PMID 26218750, 2015). "Cul4A, a scaffold protein that recruits substrates for degradation, is amplified in several human cancers, including mesothelioma." (PMID 26218750, 2015). "We next tried to evaluate the role of Cul4A on the degradation of mTOR protein in Cul4A overexpressed H28 mesothelioma cells (pBABE Cul4A), following the addition of cycloheximide." (PMID 26218750, 2015). "Among the 18 analysed mesothelioma tumour sections that showed 3–4 copies of Cul4A identified by FISH, Cul4A staining was moderate to strong in 13 samples when analysed by IHC." (PMID 26218750, 2015). "Because Gli1 expression was suggested to be critical to mesothelioma cell survival, we compared the protein expression of Cul4A and Gli1 in mesothelioma tumours and in mesothelioma cells." (PMID 26218750, 2015). "In mesothelial cell line LP-9, Cul4A protein expression is minimal compared to that in mesothelioma cells." (PMID 26218750, 2015). "Increased Cul4A copy number and Cul4A overexpression have been reported in various human cancers 2–5, and its oncogenic role has been reported in vivo and in mesothelioma cells 6,7." (PMID 26218750, 2015). "We have previously shown that Cul4A copy number and protein expression are both increased in human mesothelioma cells." (PMID 26218750, 2015). "The biological mechanism that promotes tumour cell growth by Cul4A overexpression is still under investigation, but one suggestion is that overexpressed Cul4A deregulates the cell cycle by degrading tumour suppressors p21 in mesothelioma cells." (PMID 26218750, 2015). "Next, we used Cul4A siRNA to inhibit Cul4A expression and analysed Gli1 protein expression in mesothelioma MS-1, 211H and H28 cells using western blotting." (PMID 26218750, 2015). "Although Cul4A overexpression has been suggested to promote growth of mesothelioma cells in vitro, the expression of Cul4A in mesothelioma tumour samples has not been studied." (PMID 26218750, 2015). "In this study, our results showed that Cul4A inhibition reduces mTOR protein expression in mesothelioma cells." (PMID 26218750, 2015). "In mesothelioma tumours, Cul4A and Gli1 expression were both increased compared to that in the normal pleural tissues." (PMID 26218750, 2015). "Moderate staining (++) of Cul4A and Gli1 protein expression was detected in mesothelioma H2052 cells, and minimal staining (+) of Cul4A and Gli1 protein expression was detected in mesothelial LP-9 cells." (PMID 26218750, 2015). "Quantitative analysis of western blotting images showed that both Gli1 and mTOR protein levels were decreased after Cul4A knockdown in the mesothelioma cells." (PMID 26218750, 2015). "Cul4A staining was evident on the identical regions where the mesothelioma cells with enlarged nuclei were identified." (PMID 26218750, 2015). "Mesothelioma cell lines MS-1, H28, H226, H2452 and H290 showed strong staining of Cul4A, and 211H cells showed moderate staining." (PMID 26218750, 2015). "NSCLC H1299 cell line with four copies of Cul4A and mesothelioma cell line H290 was used in this analysis." (PMID 26218750, 2015). "In mesothelioma cell lines, inhibiting Cul4A by siRNA decreased Gli1 expression, suggesting that Gli1 expression is, at least in part, regulated by Cul4A in mesothelioma cells." (PMID 26218750, 2015).
mesothelioma (continued). "Together, these results suggest that mTOR expression is, in part, regulated by Cul4A expression in the mesothelioma cells." (PMID 26218750, 2015). "Among 28 mesothelioma samples with strong Cul4A expression, 42.9% showed moderate Gli1 expression and 14.3% showed strong Gli1 expression." (PMID 26218750, 2015). "Inhibiting Cul4A expression by shRNA induces cell cycle arrest and decreases mesothelioma cell growth." (PMID 26218750, 2015). "This analysis showed 3–4 copies of Cul4A in mesothelioma cell lines MS-1 and H28, three copies in mesothelioma cell lines H226, H2452, H290 and 211H." (PMID 26218750, 2015). "In our previous studies, we have shown that Cul4A down-regulation induces cell-cycle arrest by promoting p21 protein expression in mesothelioma cells 7 and overexpression Cul4A decreased p21 protein levels in a transgenic mouse model." (PMID 26218750, 2015). "Similarly, Cul4A was overexpressed and Cul4A copy number was increased in human mesothelioma cell lines." (PMID 26218750, 2015). "Moreover, in 72.2% mesothelioma tumours with increased Cul4A copy number, Cul4A expression was moderate to strong." (PMID 26218750, 2015). "Inhibiting Cul4A by siRNA decreased Hh/Gli reporter activity in the mesothelioma H290 cells." (PMID 26218750, 2015). "We further analysed Cul4A copy number in seven human mesothelioma cell lines using FISH." (PMID 26218750, 2015). "In addition, we compared Cul4A and Gli1 expression in seven human mesothelioma cell lines, including H2452, using IHC." (PMID 26218750, 2015). "Our results suggest a linkage between Cul4A and Gli1 expression in human mesothelioma." (PMID 26218750, 2015). "Another possibility is that the increased Cul4A expression in the mesothelioma tumours may be partially driven by other biological mechanism, which has not yet studied." (PMID 26218750, 2015). "In addition, we analysed Cul4A and Gli1 protein expression in mesothelial LP-9 and mesothelioma H2052 cells using ICC." (PMID 26218750, 2015). "To further our understanding of the concurrent expression of Cul4A and Gli1 in mesothelioma samples, we investigated whether Gli1 expression can be regulated by Cul4A levels in human mesothelioma cell lines." (PMID 26218750, 2015). "Furthermore, we analysed mammalian target of rapamycin (mTOR) and Gli1 expression after Cul4A inhibition, and a potential linkage between Cul4A, mTOR and Gli1 expression in mesothelioma cells was suggested in this study." (PMID 26218750, 2015). "Increased Cul4A protein expression was detected in the Cul4A overexpressed H28 cells compared to the EV transfected control cells 7, and mTOR protein expression was significantly increased (3.5-fold) in the mesothelioma cells when Cul4A is overexpressed (*P < 0.05, t-test)." (PMID 26218750, 2015). "In this study, we sought to determine whether Cul4A is overexpressed and/or amplified in mesothelioma tumours." (PMID 26218750, 2015). "Furthermore, by revealing the Cul4A-mediated Gli1 expression in mesothelioma, our study provides a rationale for developing therapeutic agents targeting Cul4A in mesothelioma tumours." (PMID 26218750, 2015). "Targeting Cul4A in therapeutic development could decrease off-target effect and increase drug specificity to patients with Cul4A-amplified mesothelioma." (PMID 26218750, 2015). "Therefore, increased Cul4A copy number appears to, at least in part, contribute to increased Cul4A expression in mesothelioma tumours and in mesothelioma cells." (PMID 26218750, 2015). "We further studied the potential impact of increased Cul4A expression in mesothelioma cells." (PMID 26218750, 2015). "To detect whether the Cul4A gene is increased in mesothelioma tumour samples, we measured the copy number of Cul4A using FISH." (PMID 26218750, 2015).